MNX1-AS1 (MNX1 antisense RNA 1)
Synonyms: CCAT5; LOC645249; MAYA
Gene: Long non-coding RNA gene on chromosome 7 (157,007,750 to 157,017,621, forward strand). Ensembl gene ENSG00000243479.
Diseases named in the same sentence as MNX1-AS1 in open-access papers:
MNX1-AS1 is named in the same sentence as 15 diseases in open-access papers, as found by Europe PMC text mining. Sharing a sentence is not in itself a finding about the gene and the disease. The quoted sentences say what the papers report.
gastric cancer (4 papers, 2020 to 2025). A primary or metastatic malignant neoplasm involving the stomach. "A recent study has shown that the expression of lncRNA MNX1-AS1 (MNX1 antisense RNA 1) is significantly increased in gastric cancer tissues and associated with the poor prognosis of gastric cancer patients." (PMID 32460771, 2020). "The transcription regulatory gene MNX1AS1 plays a vital role in methylation process during epigenetic activation and reported to contribute in gastric cancer progression." (PMID 35831348, 2022). "Specifically, 8 genes (NRP1, MNX1AS1, SSRP1, PRDX2, PLRG1, LGALS4, SNX5 and FXYD3) were found to be highly expressed in stomach cancer tissues compared to normal tissues." (PMID 35831348, 2022).
colon cancer (2 papers, 2020 to 2023). "MNX1-AS1 was first identified as colon cancer associated transcript 5 (CCAT5) in colon cancer." (PMID 32754442, 2020).
colorectal malignant tumor (1 paper, 2021). "MNX1 antisense RNA 1 (MNX1-AS1) was firstly discovered as a highly expressed gene in colorectal malignant tumor, which is termed CCAT5 as well." (PMID 33685348, 2021).
hepatocellular carcinoma (1 paper, 2022). A malignant tumor that arises from hepatocytes. "Regarding this point, we now demonstrate that the lncRNA MNX1-AS1, also known as CCAT5, plays an essential role in regulating the non-glycolytic nuclear function of PKM2 to promote the Warburg effect in hepatocellular carcinoma (HCC)." (PMID 36476366, 2022).
hypopharyngeal carcinoma (1 paper, 2022). Carcinoma, predominantly squamous cell, arising from the epithelial cells of the hypopharynx. "Thirdly, E2F1 (E2F Transcription Factor 1) and lncRNA MNX1-AS1 (MNX1 antisense RNA 1) were up-regulated in hypopharyngeal carcinoma tissues, and reduced in hypopharyngeal carcinoma cells post acRoots incubation." (PMID 35152841, 2022).
cancer (4 papers, 2020 to 2023). A tumor composed of atypical neoplastic, often pleomorphic cells that invade other tissues. "Long non-coding RNA (LncRNA) MNX1 antisense RNA 1(MNX1-AS1) is associated with the pathology of numerous cancers." (PMID 33882027, 2021).
MNX1-AS1 also shares sentences with these, for which no sentence is quoted: breast carcinoma (6 papers); tumor (3); epithelial ovarian cancer (1); Hepatic steatosis (1); lung carcinoma (1); metastatic disease (1); non‐alcoholic fatty liver disease (1); ovarian cancer (1); stomach cancer (1).